PEMT (phosphatidylethanolamine N-methyltransferase)
Diseases named in the same sentence as PEMT in open-access papers (continued):
Sharing a sentence is not in itself a finding about the gene and the disease.
steatosis (15 papers, 2010 to 2026). Increased lipid within the cytoplasm of cells. "In instances of hepatic SAM reduction resulting from MAT deficiency or disruption of the phosphatidylethanolamine N-methyltransferase pathway, impaired phosphatidylcholine synthesis compromises lipid export, consequently leading to steatosis." (PMID 41274506, 2025). "In functional studies we showed that the HCV-induced expression of PEMT supports virus replication but also causes steatosis by modulating the expression of lipid metabolism genes." (PMID 37240132, 2023). "Furthermore, CBS deficient mice have lower levels of PC, PEMT activity, and PC/PE molar ratio; developed steatosis; and showed mild liver injury." (PMID 37123053, 2022). "In summary, our findings suggest that in chronic hepatitis C, PEMT plays a coordinating and critical role in both viral replication and the development of steatosis, by promoting the synthesis of PC." (PMID 37240132, 2023). "Regarding the tissue specific expression pattern of PEMT in humans, our results suggest an important regulatory role of PEMT in vis AT and liver tissue, especially its expression in vis, as it correlated with the severity of steatosis and diabetes." (PMID 38069170, 2023). "A previous study demonstrated that hepatic PEMT expression was significantly lower in Japanese NASH patients (n = 25) compared to individuals with simple steatosis (n = 9)." (PMID 36012560, 2022). "Hepatic PEMT expression was observed to be lower in NASH patients compared to those with simple steatosis, and was significantly correlated with platelet counts, which typically decline with advancing fibrosis." (PMID 36012560, 2022). "Reduced expression of hepatic phosphatidylethanolamine N-methyltransferase (PEMT), which catalyzes the production of phosphatidylcholine, causes steatosis, inflammation, and fibrosis in mice." (PMID 36012560, 2022). "Consistent with increased AHR and PEMT expression in steatosis patients, hepatic PC levels were modestly, but significantly, increased, and PE levels were decreased resulting in an increased ratio of PC/PE." (PMID 29416063, 2018). "PEMT mRNA expression in liver tissues of NASH patients was significantly lower than those with simple steatosis and we postulated the distinct clinical entity of lean NASH with insufficiency of PEMT activities." (PMID 26883167, 2016). "Our study establishes that PEMT deficiency is sufficient to initiate and drive the complete progression from steatosis to advanced liver fibrosis, identifying PEMT as a critical metabolic checkpoint and a potent therapeutic target for mitigating progressive liver disease." (PMID 42275195, 2026). "As well as supporting virus replication, PEMT mediates steatosis." (PMID 37240132, 2023). "To determine if hepatic expression of PEMT and the PC/PE ratio are also aberrantly elevated in NAFLD steatosis patients, we measured mRNA levels of PEMT, AHR, and SHP in liver samples from 15 normal individuals, 15 simple steatosis patients, and 15 severe NASH-fibrosis patients." (PMID 29416063, 2018). "PEMT knockout mice do not display any PEMT activity in the liver and depend completely on dietary choline intake, and when fed a choline-deficient diet develop severe steatosis." (PMID 23394097, 2013). "Phosphatidylethanolamine N-methyltransferase (PEMT) knockout mice have altered phosphatidylcholine levels and steatosis as well as compromised very low density lipoprotein (VLDL) assembly and impaired secretion." (PMID 32908189, 2020). "Finally, PEMT mRNA expression in liver tissues of NASH patients was significantly lower than simple steatosis and we postulated presence of distinct clinical entity of lean NASH with insufficiency of PEMT activities." (PMID 26883167, 2016). "The major novel finding in our study is that PEMT plays a key role in HCV replication and its genotype-specific induction of steatosis, through the non-canonical synthesis of PC." (PMID 37240132, 2023).
steatosis (continued). "In mice lacking phosphatidylethanolamine N-methyltransferase (PEMT), fenofibrate treatment completely prevented MAFLD development and partially reversed steatosis and fibrosis in already established MAFLD in this model." (PMID 36148775, 2022).
hepatoma (11 papers, 2014 to 2024). "Immunohistochemical analysis revealed lower PEMT expression in hepatocellular carcinoma from patients with concurrent gout compared to those without (P < .05)." (PMID 39533594, 2024). "PEMT is also involved in other cancers, in addition to hepatocellular carcinoma, and current studies have found several important SNPs in both bladder and breast cancers." (PMID 37191416, 2023). "PEMT gene expression and activity are downregulated in patients with hepatic carcinoma, and PEMT expression is significantly upregulated in patients with non-small-cell lung cancer." (PMID 35782075, 2022). "Chemically induced hepatocarcinogenesis and growth of hepatoma cells in host animals also demonstrated opposing activities of PEMT and CT." (PMID 28083512, 2016). "When growing hepatoma cells in an animal host, PEMT activity and protein expression were barely detected in the fast proliferation stage, while its mRNA and protein reappeared in stationary growth stages." (PMID 28083512, 2016). "The first indication that PEMT can suppress cancer was the discovery that the growth of rat hepatoma cells was suppressed by overexpressing the PEMT gene." (PMID 28083512, 2016). "A positive correlation between mitochondrial ATP and PE contents in hepatoma cells has been demonstrated, together with an increased respiratory rate after downregulation of phosphatidylethanolamine N-methyltransferase (PEMT) that results in the elevation of mitochondrial PE content." (PMID 38892240, 2024). "Transcriptome research revealed that PEMT, which was downregulated in hepatocellular carcinoma, may contribute to the suppression of this cancer and is positively associated with progression-free survival." (PMID 39533594, 2024). "Interestingly, expression of the two forms of PEMT in a hepatoma cell line demonstrated a 40% lower specific activity of the Met isoform relative to the Val isoform, indicating a functional consequence of the substitution." (PMID 36012560, 2022). "However, in the PEMT knockout mice, the CDP-choline pathway is upregulated, whereas during the PEMT overexpression in hepatoma cells, it is downregulated, showing a strong link of the PEMT pathway with the liver PC metabolism." (PMID 24578708, 2014). "PEMT is highly expressed in normal liver, but its activity was negligible in the two hepatoma cell lines and almost diminished during chemically induced hepatocarcinogenesis, and the induced neoplastic phenotype could be partially reversed by PEMT cDNA transfection." (PMID 28083512, 2016). "Most early studies of PEMT function were using non-human hepatoma cells or chemically induced hepatocarcinogenesis models in animals." (PMID 28083512, 2016). "When PEMT was overexpressed in McArdle-RH7777 rat hepatoma cells, cellular PtdCho levels did not change even though [methyl-3H]methionine and [3H]ethanolamine were incorporated into PtdCho, suggesting that conversion of PtdEtn to PtdCho occurred." (PMID 28083512, 2016). "The molecular mechanisms by which PEMT expression suppresses hepatoma growth are not yet fully understood." (PMID 28083512, 2016). "In addition, it was reported that hexadecylphosphocholine, the alkylphospholipid analog, reduces cell proliferation in hepatoma cells and simultaneously inhibits PC synthesis via the CDP-choline and PEMT pathways." (PMID 24932311, 2014). "A later study with clinical samples of human hepatocellular carcinomas (HCC) showed that while the PEMT gene was intact, its mRNA level was reduced or even absent compared to peritumoral normal tissue, which was also observed in parallel for PEMT’s enzyme activity." (PMID 28083512, 2016).
breast carcinoma (8 papers, 2014 to 2026). "A polymorphism in the SNP rs12325817 within the PEMT gene is linked to an increased risk of developing breast cancer." (PMID 39409074, 2024). "A functional polymorphism of the PEMT gene, rs7946, has been reported to be associated with breast cancer risk, and significant interactions were observed between choline intake and betaine intake." (PMID 38351975, 2024). "In BRCA1-mutated breast cancer, the PEMT gene undergoes epigenetic repression, and hypermethylation of a specific site in the PEMT promoter is associated with histological grade and estrogen receptor status." (PMID 28083512, 2016). "While early studies of PEMT’s role in cancer were mostly observed in liver cancers, more recent studies indicated that PEMT polymorphism is also related to breast cancer risk." (PMID 28083512, 2016). "Based on the results above, we further explored the relationship between -132 site methylation and PEMT expression in BRCA1-mutated breast cancer specimens." (PMID 24675476, 2014). "This study provides new insights into the causes and prognosis of PEMT inactivation in BRCA1-mutated breast cancer." (PMID 24675476, 2014). "It is interesting to note that functional polymorphisms of the PEMT gene play an important role in breast cancer development." (PMID 24675476, 2014). "Two studies have evaluated the associations between PEMT rs7946 and breast cancer." (PMID 38351975, 2024). "Additionally, the hypermethylation of the -132 site in the PEMT promoter occurs in breast cancer type 1 susceptibility gene (BRCA1)-mutated breast cancer cells, resulting in reduced enzyme expression." (PMID 39409074, 2024). "In addition, expression levels of PEMT were decreased in BRCA1-mutated breast cancer compared to their adjacent normal breast tissues." (PMID 24675476, 2014). "Furthermore, PEMT promoter polymorphism, −774G>C, which results in lower PEMT expression and choline deficiency, was associated with increased breast cancer risk among women receiving hormone replacement therapy." (PMID 24932311, 2014). "Notably, -132 was the critical site for PEMT transcription only in primary BRCA1-mutated breast cancer cells (Fig. 3Bii)." (PMID 24675476, 2014). "In the ebi-a-GCST90018799 cohort, genes with causal relationships to breast cancer included NOP58, OCIAD2, P4HA2, PEMT, and PNPLA2." (PMID 41424847, 2026). "Of note, FBXW7 and PEMT are both down-regulated in breast cancer and they share a proposed SLI in HYGIN." (PMID 31351478, 2019). "Phosphatidylethanolamine N-methyltransferase (PEMT) plays a critical role in breast cancer progression." (PMID 24675476, 2014). "In this study, we report that the first-promoter-specific transcript 1 is the major PEMT mRNA species in human breast tissues, and that methylation of the -132 site is a key regulatory element for PEMT transcription in BRCA1-mutated breast cancer." (PMID 24675476, 2014). "Here, we show that the first promoter-specific transcript 1 is the major PEMT mRNA species, and methylation of the -132 site is a key regulatory element for the PEMT gene in BRCA1-mutated breast cancer." (PMID 24675476, 2014). "In the LIBCSP study, although neither PEMT rs7946 nor betaine intake were independently related to breast cancer risk, a significant interaction between this variant and dietary betaine intake was found (P < 0.05)." (PMID 38351975, 2024). "However, PEMT gene methylation does not correlate with prognoses in patients with BRCA1-mutated breast cancer." (PMID 39409074, 2024). "Another case–control study showed PEMT rs7946 has no overall association with breast cancer, but a significant interaction was observed between choline intake and PEMT rs7946 (P-interaction = 0.029) in relation to breast cancer risk." (PMID 38351975, 2024). "To investigate the epigenetic regulation of PEMT, we compared the DNA methylation patterns of three promoters between BRCA1-mutated or non-mutated breast cancer and their adjacent normal breast tissues." (PMID 24675476, 2014).
breast carcinoma (continued). "Breast cancer cells lacking STARD7 do not have enough PC in mitochondria and may therefore try to synthetize PC from Phosphatidylethanolamine (PE) through a cascade of reactions relying on Phosphatidylethanolamine N‐Methyl Transferase (PEMT) and on SAM." (PMID 40443279, 2025).
non-alcoholic fatty liver disease (8 papers, 2020 to 2026). "PEMT deficiency in Pemt −/− mice showed resistance to high-fat- and high-glucose-induced obesity and diabetes, whereas insufficient PEMT was associated with increased risk of nonalcoholic fatty liver disease." (PMID 32399287, 2020). "PEMT-mediated alterations in the PC/ phosphatidylethanolamine (PE) ratio are associated with the development and progression of non-alcoholic fatty liver disease (NAFLD) and its successor, non-alcoholic steatohepatitis (NASH), as well as liver failure and impaired liver regeneration in humans." (PMID 38069170, 2023). "Furthermore, a loss-of-function mutation of PEMT in humans may be associated with non-alcoholic fatty liver disease (NAFLD) as a possible consequence of altered PC synthesis and an increased TG accumulation." (PMID 36139111, 2022). "PEMT knockout decreases the hepatic PC/PE ratio in non-alcoholic fatty liver disease mice and decreases their survival rates after PHx 52, suggesting that high PE levels impair liver regeneration." (PMID 41346700, 2026).
Hepatic fibrosis (7 papers, 2016 to 2026). The presence of excessive fibrous connective tissue in the liver. "In logistic regression analyses, lower gene expression of cystathionine beta-synthase (CBS) and phosphatidylethanolamine N-methyltransferase (PEMT) was associated with a higher risk of hepatic fibrosis." (PMID 41180856, 2025). "Reduced MAT1A and PEMT expression were also observed in patients with NASH and liver fibrosis." (PMID 39795274, 2024).
atherosclerosis (6 papers, 2011 to 2024). A disease characterized by the build-up of fatty material and calcium deposition in the arterial wall resulting in partial or complete occlusion of the arterial lumen. "PEMT deficiency in ApoE−/− mice decreases the PC biosynthesis and attenuates atherosclerosis." (PMID 31379582, 2019). "Consequently, these findings suggest that medications acting as PEMT inhibitors hold promise for use in the treatment or prevention of atherosclerosis." (PMID 39409074, 2024).
diabetes (6 papers, 2016 to 2024). "We further investigated the association between PEMT mRNA expression and various metabolic phenotypes, including parameters related to diabetes, lipids, inflammation and adipokines." (PMID 38069170, 2023). "The rs4646404 was associated with vis AT PEMT expression and also with diabetes-related traits." (PMID 38069170, 2023). "This suggests that reduced PEMT activity is not sufficient to cause NAFLD, but could make subjects more susceptible to developing NAFLD when other risk factors, such as diabetes, low dietary choline intake, or excess calorie intake, come into play." (PMID 28159867, 2017).
liver disease (6 papers, 2017 to 2026). "While human PEMT loss-of-function polymorphisms are linked to increased metabolic dysfunction-associated steatotic liver disease (MASLD) risk, the enzyme's role as a primary driver of progressive liver disease remains underexplored." (PMID 42275195, 2026). "Moreover, this patient possessed another deleterious variant: PEMT p.Arg226Trp which could predispose to the development of liver disease in the early years of life." (PMID 28626473, 2017). "Defects in transsulfuration pathway, such as CBS deficiency, promote elevated Hcy, SAH and SAMe thereby destabilizing SAMe homeostasis, with diminished SAMe/SAH ratio, reduced GSH and lower PEMT activity which can promote the setting of mild steatotic liver disease (SLD)." (PMID 39941901, 2025). "Additionally, PEMT expression was examined in vis, sc AT and liver tissue in a separate cohort of 64 patients with morbid obesity and liver disease." (PMID 38069170, 2023). "Finally, to discern the correlation between PEMT mRNA expression and liver disease/dysfunction across distinct tissues, we aimed to identify whether there is a single tissue important for NASH development." (PMID 38069170, 2023). "The PE N-methyltransferase (PEMT) pathway uses SAMe to methylate PE yielding PC and being affected by both SAMe increase and depletion which ultimately can lead to dysregulation of VLDL secretion and result in liver disease, atherosclerosis and obesity." (PMID 39941901, 2025).
renal fibrosis (5 papers, 2022 to 2025). A final common manifestation of a wide variety of chronic kidney diseases characterized by glomerulosclerosis and tubulointerstitial fibrosis. "HDAC4-induced renal fibrosis was associated with renal tubular cell injury and apoptosis, promotion of pEMT, and preserving the Klotho expression at transcriptional levels." (PMID 35847036, 2022). "Further mechanistic investigations are required to clarify the contribution of pEMT to renal fibrosis." (PMID 40131218, 2025). "In this study, we demonstrate that pharmacological and genetic inhibition of HDAC4 attenuates renal fibrosis and suppresses the molecular mechanisms leading to renal fibrosis, including the pEMT, fibroblast activation, and activation of the TGF-β1/Smad3, STAT3, and ERK1/2 signaling pathways." (PMID 35847036, 2022). "Indeed, we found that the UUO-induced downregulation of these molecules was largely reversed by global deletion of HDAC11, indicating that HDAC11 may contribute to pEMT and renal fibrosis by suppressing the expression of multiple renoprotective factors." (PMID 41275091, 2025). "Finally, suppression of renoprotective molecules may constitute another mechanism by which HDAC11 promotes pEMT and renal fibrosis." (PMID 40386380, 2025). "In light of this, therapeutic targeting of pEMT is proposed as an approach to promote kidney repair and regeneration as it targets a primary pathology underlying renal failure rather than addressing renal fibrosis, which is consequential." (PMID 37816442, 2023).
hyperhomocysteinemia (4 papers, 2015 to 2020). A serious metabolic condition caused by mutations in the MTHFR gene, medications, or nutritional deficiency. "Hypomethylation associated with hyperhomocysteinemia was related to lipid accumulation in tissues, elevated Hcy increased SAH level thus inhibited PEMT and lower the production of PC from phosphatidylethanolamine." (PMID 26337056, 2015). "Further, to determine the relationship between 1-carbon metabolism, methylation, and hyperhomocysteinemia (HHcy), we measured DNMT, BHMT, and PEMT." (PMID 33708132, 2020). "A similar relationship between methionine metabolism and PEMT features in a putative relationship between hyperlipidemia and hyperhomocysteinemia but has not previously been described in heat stress." (PMID 30365526, 2018).
liver dysfunction (4 papers, 2010 to 2023). "Regarding the PEMT gene, several studies have demonstrated an increased risk of developing liver dysfunction and NAFLD when choline intake is deficient in carriers of the variants rs12325817 and rs7946." (PMID 36830856, 2023). "It is therefore quite possible that there is some inhibition of PEMT in the MKO cbs null mice that has the potential to contribute to hepatopathy." (PMID 20638879, 2010).
non-alcoholic steatohepatitis (4 papers, 2016 to 2023). "Hepatic PEMT expression was reduced in NAFLD patients with inflammation and fibrosis (i.e., nonalcoholic steatohepatitis or NASH) compared to participants with normal liver histology (β = −1.497; p = 0.005)." (PMID 36012560, 2022).